ZMPSTE24 (zinc metallopeptidase STE24)
Diseases named in the same sentence as ZMPSTE24 in open-access papers (continued):
Sharing a sentence is not in itself a finding about the gene and the disease.
laminopathies (24 papers, 2009 to 2025). "Overlapping but distinct phenotypes have been noted in ZMPSTE24 deficiency and other laminopathies caused by LMNA pathogenic variants, such as Emery-Dreifuss muscular dystrophy." (PMID 40644604, 2025). "Patients affected with FPLD2 and MADB, two other laminopathies linked to lamin A and ZMPSTE24 mutations, respectively, also suffer from lipodystrophy." (PMID 37408186, 2023). "We examined nuclear morphology in our patient fibroblast panel, since abnormal nuclear shape is known to be a hallmark of many LMNA- and ZMPSTE24-linked laminopathies." (PMID 38050983, 2023). "Restrictive dermopathy (RD) and mandibuloacral dysplasia-type B (MAD-B) are recessive progeroid laminopathies that result from mutations in ZMPSTE24 and lead to accumulation of permanently farnesylated and carboxyl methylated full-length prelamin A." (PMID 38050983, 2023). "Mutations in the ZMPSTE24 gene give rise to several laminopathies, reproduced to a large extent in ZMPSTE24-deficient mice." (PMID 31666429, 2019). "MADB (MIM: #608612) is a secondary laminopathy, resulting from homozygous variants in zinc metalloprotease ZMPSTE24 (1p34.2)." (PMID 29557732, 2018). "Primary laminopathies include those diseases caused by variants in LMNA, whilst secondary laminopathies are caused by variants in other genes encoding proteins which are playing some role in prelamin A maturation (ZMPSTE24) or in lamin A/C function (BANF1)." (PMID 29557732, 2018). "The primary laminopathies are due to mutations in the Lmna gene and secondary laminopathies are caused by mutations in the Zmpste24 gene." (PMID 26232943, 2015). "For example, laminopathy-based premature aging syndromes (collectively known as laminopathies) originate from mutations in the LMNA gene or ZMPSTE24 gene." (PMID 25907989, 2015). "Finally, using a selected battery of laminopathy-associated lamin A mutants, Zmpste24−/− null cells and ZMPSTE24 inhibitors, we found that PL-1C7 can distinguish among different mutant effects on the protein levels of prelamin A." (PMID 26900797, 2016). "Mutations of lamin A/C (Lmna) gene or the Zmpste24 gene produce abnormal lamins, such as progerin or prelamin A, respectively, which can cause disassembly of the nuclear envelope proteins, subsequently accompanied by accelerated aging due to laminopathies." (PMID 26232943, 2015). "Unfortunately, PI treatment can also impair maturation of LMNA by inhibiting the activity of ZMPSTE24, thus inducing laminopathies in a manner similar to progeroid disorders." (PMID 37731189, 2024). "In a subset of progeroid laminopathies, in MADB and RD for example, the disease is caused by compound heterozygous and homozygous mutations in FACE1 gene that encodes for Zmpste24." (PMID 29936894, 2018). "Hereditary and sporadic laminopathies are caused by mutations in genes encoding lamins, their partners, or the metalloprotease ZMPSTE24/FACE1." (PMID 29696758, 2018). "We found that Foxa2 occupancy is also increased in Zmpste24 mutant mice, a laminopathy model, connecting our findings to Foxa2 binding in old livers." (PMID 29484800, 2018). "We also show that Foxa2 binds more sites in Zmpste24 mutant mice, a progeroid laminopathy model, similar to increased Foxa2 occupancy in old livers." (PMID 29484800, 2018). "As animal models employed in studies on secondary laminopathies, Zmpste24-knockout mice (Zmpste24−/− mice) are well-known." (PMID 26232943, 2015). "Mice with knockout of the Zmpste24 gene (Zmpste24−/−), which is responsible for posttranslational processing and cleavage of prelamin A, exhibit premature aging and a phenotype characteristic of patients with rare hereditary laminopathies." (PMID 38534394, 2024). "Diseases involving lamin proteins are called laminopathies and can be primary or secondary Primary laminopathies are caused by mutation of the LMNA gene, and secondary laminopathies are caused by Zmpste24 defects, which prevents prelamin A from successfully being converted to lamin A." (PMID 33316938, 2020).
laminopathies (continued). "Interestingly, resveratrol has been shown to improve bone mineral density from zinc metallopeptidase, STE24 (Zmpste24) knockout mice, a mouse laminopathy model of premature aging." (PMID 30257716, 2018). "We show here that a central obesity without subcutaneous lipoatrophy is associated with a laminopathy due to a heterozygous missense mutation in ZMPSTE24." (PMID 27120622, 2016). "Thus, we suggest that clarification of terms used to refer to laminopathies and/or specific LMNA and ZMPSTE24 mutations could be helpful for patients, their health-care providers, and researchers in the laminopathy field." (PMID 38050983, 2023). "Notably, lethal neonatal laminopathies have now been identified and are caused by some specific mutations in the LMNA and ZMPSTE24/FACE-1 genes, suggesting that certain developmental abnormalities may be involved in some cases." (PMID 21479207, 2011).
mandibuloacral dysplasia (16 papers, 2013 to 2025). Mandibuloacral dysplasia (MAD) is a rare genetic bone disorder characterized by growth delay, postnatal development of craniofacial anomalies including mandibular hypoplasia, progressive acral osteolysis, mottled or patchy pigmentation, skin atrophy, and partial or generalized lipodystrophy. "ZMPSTE24 mutations also underlie mandibuloacral dysplasia (MAD) and restrictive dermopathy (RD), which is a mild progeroid disorder, and a severe developmental disorder, respectively." (PMID 32910507, 2020). "Co-existence of mandibuloacral dysplasia and focal segmental glomerulosclerosis has been reported in two patients with ZMPSTE24 deficiencies." (PMID 31293201, 2019). "Here the case of a boy affected with mandibuloacral dysplasia and compound heterozygous mutations in ZMPSTE24 is presented." (PMID 30548811, 2019). "Mutations in the ZMPSTE24 gene cause mandibuloacral dysplasia (MAD) and restrictive dermopathy (RD)." (PMID 30140252, 2018). "Mandibuloacral dysplasia associated with B-type lipodystrophy or MAD-B (also known as “atypical HGPS”) is the less severe form of diseases caused by ZMPSTE24 mutations." (PMID 28854936, 2017). "So called laminopathies such as Hutchinson–Gilford-progeria-syndrome (HGPS), atypical WS, restrictive dermopathy (RD), and mandibuloacral dysplasia (MAD) are caused by mutations in lamin A and the ZMPSTE24 farnesyltransferase required for lamin A processing." (PMID 23443494, 2013). "HGPS has also been studied in prelamin A-expressing Zmpste24-/- mice, whose phenotype closely resembles type B mandibuloacral dysplasia." (PMID 30900948, 2019). "Apart from some atypical progeroid forms there are three major syndromes caused by LMNA or ZMPSTE24 mutations: Hutchinson Gilford progeria syndrome (HGPS), Mandibuloacral Dysplasia (MAD) and Restrictive Dermopathy (RD)." (PMID 23804595, 2013). "Finally, a patient affected with Mandibuloacral Dysplasia type B (MAD-B, carrying a homozygous mutation in ZMPSTE24, encoding an enzyme involved in Prelamin A maturation, leading to accumulation of wild type farnesylated Prelamin A), was also included in this study." (PMID 27409638, 2016). "Familial partial lipodystrophy with mandibuloacral dysplasia (MAD), on the other hand, is a rare autosomal recessive disease that is due to mutations in the lamin A/C gene (LMNA) and mutations in the zinc metalloproteinase gene (ZMPSTE24)." (PMID 33233602, 2020).
restrictive dermopathy (16 papers, 2009 to 2026). "ZMPSTE24 encodes the only metalloprotease, which transforms prelamin into mature lamin A. Up to now, mutations in ZMPSTE24 have been linked to Restrictive Dermopathy (RD), Progeria or Mandibulo-Acral Dysplasia (MAD)." (PMID 27120622, 2016). "Altogether, only 17 genes were primarily identified in relation to cervical insufficiency, with six being syndromic, i.e. COL1A1 and COL3A1 causing EDS; FBN1 causing Marfan syndrome; ZMPSTE24 and LMNA causing restrictive dermopathy; and MATR3 causing myopathy." (PMID 32214361, 2020). "Mutations causing an enzyme dysfunction in ZMPSTE24 also result in HGPS related premature aging disorders like mandibuloacral–dysplasia type B and restrictive dermopathy." (PMID 32872320, 2020). "The total absence of ZMPSTE24 results in the higher amount of prelamin A and to the most severe phenotype, the lethal neonatal Restrictive Dermopathy (RD)." (PMID 27120622, 2016).
lipodystrophy (12 papers, 2012 to 2025). A congenital or acquired disorder characterized by abnormal loss or redistribution of the adipose tissue in the body. "As said above, mutations in lamin A/C, lamin B2, or ZMPSTE24 gene or alterations of prelamin A maturation are the cause of laminopathies featuring lipodystrophy." (PMID 30781376, 2019). "Lopinavir also inhibits ZMPSTE24, thereby blocking lamin A biogenesis and leading to an accumulation of prelamin A. ZMPSTE24 deficiency in humans causes an accumulation of prelamin A and leads to lipodystrophy and premature aging, which perhaps causes senescence phenotype in our cultured neurons." (PMID 34953016, 2022). "We directly sequenced all exons of genes associated with lipodystrophy including LMNA, ZMPSTE24, AGPAT2, BSCL2, CAV1, PTRF, and PPARγ2." (PMID 31293201, 2019). "Mutations in several genes have been found in patients with inherited lipodystrophies, including mutations in LMNA, PPARG, AKT2 and ZMPSTE24 in partial lipodystrophy, and mutations in AGPAT2, BSCL2, CAV1 and PTRF in congenital total lipodystrophy." (PMID 26987365, 2016). "Unlike earlier treatments, INSTIs have significantly reduced the incidence of lipodystrophy as a side effect while effectively managing HIV infection, as they do not inhibit ZMPSTE24 protease activity." (PMID 39125589, 2024).
osteoporosis (7 papers, 2011 to 2026). A condition of reduced bone mass, with decreased cortical thickness and a decrease in the number and size of the trabeculae of cancellous bone (but normal chemical composition), resulting in increased fracture incidence. "The availability of Zmpste24‐deficient mice could provide a new model to aid the study of mechanistic events underlying age‐related osteoporosis." (PMID 31120193, 2019). "In addition to classic premature aging syndromes, Zmpste24 has recently been found to play an important role in several age-related diseases, such as osteoarthritis, osteoporosis, and atherosclerosis." (PMID 41522494, 2026). "Zinc metalloproteinase Ste24 homolog (Zmpste24) is an endoprotease with a critical role in the maturation of lamin A protein, and Zmpste24 KO mice exhibit growth retardation, alopecia, muscle weakness, osteoporosis and premature death, all of which are features of HGPS." (PMID 38816549, 2024). "Moreover, activating Cav1.2 channel mitigated osteoporosis symptom in Zmpste24−/− mice." (PMID 31120193, 2019). "Furthermore, mice lacking the enzyme responsible for lamin A/C processing (Zmpste24−/−) show accelerated bone loss and the typical features of senile osteoporosis." (PMID 21547077, 2011).
cardiomyopathy (5 papers, 2016 to 2020). A disease of the heart muscle or myocardium proper. "Additionally, a mutation in ZMPSTE24 known to confer a reduction in enzyme activity was found in a patient with metabolic syndrome and cardiomyopathy." (PMID 31622279, 2019). "Dilated cardiomyopathy has however been reported in ZMPSTE24-deficient mice." (PMID 31856865, 2019). "In this regard, a recently published study links inhibition of ZMPSTE24 activity by protease treatment in HIV patients with increased levels of premature prelamin A mediating myocardial inflammation and HIV-associated cardiomyopathy." (PMID 32872320, 2020). "However, one key difference is the model we used relied on mutating the site of ZMPSTE24 cleavage and, therefore, does not fully model the problem in HIV-associated cardiomyopathy, where a Zmpste24-KO or HIV PI pharmacological intervention would be interesting for further study." (PMID 31622279, 2019).
premature aging syndrome (5 papers, 2020 to 2026). Changes in the organism associated with senescence, occurring at an accelerated rate. "MADB is a rare premature aging syndrome caused by a heterozygous mutation in the ZMPSTE24 gene on chromosome 1p34 encoding the enzyme zinc metalloprotease ZMPSTE24." (PMID 37408186, 2023). "In HGPS, genetic mutations in the LMNA or ZMPSTE24 gene lead to defective processing of prelamin A, resulting in premature aging syndromes." (PMID 37256358, 2023). "For this purpose, we used a mouse model in which the absence of Zmpste24 metalloproteinase leads to a progeroid phenotype similar to the human premature aging syndrome." (PMID 34448355, 2021).
viral infection (5 papers, 2017 to 2024). "Among these genes, the critical role of ZMPSTE24 in response to viral infections has been well-documented." (PMID 38200094, 2024). "ZMPSTE24 is a restriction factor for a live virus infection with the coronavirus mouse hepatitis virus." (PMID 36197088, 2022). "Interestingly, Dorf and colleagues reported that MEFs knocked out for Ifitm1-3 that overexpressed human ZMPSTE24 were resistant to infection by multiple viruses, but MEFs knocked out for Zmpste24 that overexpressed IFITM3 were sensitive to viral infection." (PMID 36197088, 2022). "Notably, CRISPR-Cas9-mediated knockout of ZMPSTE24 in human alveolar epithelial A549 cells increased arenavirus glycoprotein-mediated viral entry in pseudoparticle assays and live virus infection models." (PMID 35283811, 2022). "Consistently, PKP2, FKBP8, TRIM41 and ZMPSTE24 inhibited viral infection of NY/2009 and WSN/33." (PMID 28169297, 2017). "Thus, ZMPSTE24-mediated restriction activity is involved in the early stages of the innate immune response to arenavirus infection and IFITMs are able to enhance the effects on membrane fluidity and thus inhibition of virus infection." (PMID 35283811, 2022). "Thus, it is tempting speculate that a low level of ZMPSTE24 could contribute to increased vulnerability to viral infection in aging individuals." (PMID 36197088, 2022). "To examine the activity of ZMPSTE24 in the context of a live virus infection, we assessed intracellular MOPV L and NP gene expression and infectious MOPV production over 72 h in the A549 ZMPSTE24 KO cells and KO cells overexpressing ZMPSTE24-FLAG." (PMID 35283811, 2022). "Up to this point, our conclusion that ZMPSTE24 can act as a coronavirus restriction factor was based on SARS-CoV-2 Spike-mediated pseudovirus or cell fusion assays, which may not reflect a true live viral infection." (PMID 36197088, 2022).
osteoarthritis (4 papers, 2020 to 2026). A noninflammatory degenerative joint disease occurring chiefly in older persons, characterized by degeneration of the articular cartilage, hypertrophy of bone at the margins and changes in the synovial membrane. "Further studies exhibited that loss of Zmpste24 in mesenchymal stem cells and chondrocytes brought about severe osteoarthritis." (PMID 37217512, 2023). "The deletion of Zmpste24 in MSCs and cartilage causes severe osteoarthritis with decreased cell proliferation and accelerated cell senescence." (PMID 37217512, 2023). "Zmpste24 will be one of the effective targets for the treatment of osteoarthritis, and the use of this animal model will accelerate the study of the pathogenic mechanism of aging osteoarthritis." (PMID 37217512, 2023). "GSK126 can partially alleviate osteoarthritis caused by Zmpste24 deletion." (PMID 37217512, 2023). "Loss of Zmpste24 in articular cartilage could exacerbate the occurrence and development of osteoarthritis." (PMID 37217512, 2023). "Blocking these inflammatory factors may have a certain alleviation effect on osteoarthritis caused by Zmpste24 deficiency." (PMID 37217512, 2023). "During aging-related osteoarthritis progression, reduced Zmpste24 expression in chondrocytes promotes presenilin accumulation, inhibits cell proliferation, and accelerates cellular senescence." (PMID 41522494, 2026). "In conclusion, through a retrospective cohort analysis, cellular functional assays, and in vivo animal studies, we demonstrated that PIs, particularly lopinavir, lead to the early onset of osteoarthritis symptoms by inhibiting Zmpste24." (PMID 40461512, 2025). "OA Research Society International (OARSI) histopathological scores showed that Zmpste24 deletion exacerbated the development of osteoarthritis." (PMID 37217512, 2023). "To determine the contribution of Zmpste24 to the occurrence and development of osteoarthritis in vivo, we constructed Zmpste24 transgenic knockout mice." (PMID 37217512, 2023). "Previous studies showed that Zmpste24 inhibits chondrocyte senescence and reduces osteoarthritis." (PMID 41522494, 2026).
partial lipodystrophy (4 papers, 2016 to 2024). Loss and redistribution of subcutaneous and/or visceral adipose tissue from specific regions of the body. "In the present study, we describe the detailed phenotype of partial lipodystrophy with senescence features associated with a heterozygous missense mutation in ZMPSTE24 and prelamin A accumulation." (PMID 27120622, 2016). "A notable phenotypic difference lies in the specific association of LMNA variants with partial lipodystrophy (MADA) and ZMPSTE24 variants with generalised lipodystrophy (MADB)." (PMID 39273270, 2024).
arenavirus infection (2 papers, 2022). "Given that previous studies have showed that ZMPSTE24 is required for the antiviral activity of IFITMs, we explored a possible cooperative role of ZMPSTE24 and IFITMs against arenavirus infection." (PMID 35283811, 2022). "Expression of ZMPSTE24-FLAG in these KO cells dramatically decreased intracellular virus genome and infectious virus production demonstrating a significant antiviral role of ZMPSTE24 during live arenavirus infection." (PMID 35283811, 2022). "Collectively, our findings define the role of ZMPSTE24 host restriction activity in the early stages of arenavirus infection." (PMID 35283811, 2022). "The antiviral impact of ZMPSTE24 on arenavirus infection was shown by demonstrating that arenavirus GPpp infection and MOPV replication are enhanced in cells with depleted ZMPSTE24 and that ectopic expression of ZMPSTE24 caused a reduction in arenavirus GPpp and MOPV infection." (PMID 35283811, 2022). "A recent report found that IFITMs act cooperatively with ZMPSTE24 to restrict arenavirus infection." (PMID 36197088, 2022). "To date, there is limited information about how arenavirus infections may be antagonised by cell intrinsic factors, and the putative role of ZMPSTE24 in arenavirus biology has not yet been explored." (PMID 35283811, 2022).
atherosclerosis (2 papers, 2016 to 2026). A disease characterized by the build-up of fatty material and calcium deposition in the arterial wall resulting in partial or complete occlusion of the arterial lumen. "In addition, it has been shown recently that ZMPSTE24 downregulation is, in itself, a major contributor in Vascular Smooth Muscle Cell dysfunctions that could translate into early atherosclerosis at the clinical level." (PMID 27120622, 2016).
degenerative disc disease (2 papers, 2019 to 2026). "Our experiments confirmed this: blocking or deleting Zmpste24 accelerates NP cell senescence and lumbar disc degeneration." (PMID 41522494, 2026). "We initially isolated NP cells from patients with IVDD and observed a significant inverse correlation between Zmpste24 downregulation and the severity of disc degeneration." (PMID 41522494, 2026). "Therefore, future studies are needed to assess the molecular pathway(s) involved in the MSC-induced upregulation of ZMPSTE24 in NPCs, and on BMSCs’ paracrine regulation of senescence-related pathways in degenerative disc disease." (PMID 31666429, 2019). "Our findings suggest the protective role of Zmpste24 in IVDD and provide a foundation for developing new therapies of patients with disc degeneration." (PMID 41522494, 2026).